DNAJC6 (DnaJ heat shock protein family (Hsp40) member C6)
Description:
May act as a protein phosphatase and/or a lipid phosphatase. Co-chaperone that recruits HSPA8/HSC70 to clathrin-coated vesicles (CCVs) and promotes the ATP-dependent dissociation of clathrin from CCVs and participates in clathrin-mediated endocytosis of synaptic vesicles and their recycling and also in intracellular trafficking. Firstly, binds tightly to the clathrin cages, at a ratio of one DNAJC6 per clathrin triskelion. The HSPA8:ATP complex then binds to the clathrin-auxilin cage, initially at a ratio of one HSPA8 per triskelion leading to ATP hydrolysis stimulation and causing a conformational change in the HSPA8. This cycle is repeated three times to drive to a complex containing the clathrin-auxilin cage associated to three HSPA8:ADP complex. The ATP hydrolysis of the third HSPA8:ATP complex leads to a concerted dismantling of the cage into component triskelia. Then, dissociates from the released triskelia and be recycled to initiate another cycle of HSPA8's recruitment. Also acts during the early steps of clathrin-coated vesicle (CCV) formation through its interaction with the GTP bound form of DNM1 (By similarity).
Synonyms: KIAA0473; PARK19; DJC6
Tractability: Antibody: the Human Protein Atlas places it where antibodies can reach. PROTAC: ubiquitination databases record sites on it; its protein half-life has been measured.
Gene: Protein-coding gene on chromosome 1 (65,248,219 to 65,415,871, forward strand). Ensembl gene ENSG00000116675.
Subcellular location: Cytoplasmic vesicle, clathrin-coated vesicle
Subcellular location (Human Protein Atlas): Cytosol; Nucleoplasm; Plasma membrane
Pathways (Reactome):
Vesicle-mediated transport: Clathrin-mediated endocytosis; Golgi Associated Vesicle Biogenesis; Lysosome Vesicle Biogenesis
Gene Ontology:
Molecular function: protein binding; clathrin binding; clathrin heavy chain binding; heat shock protein binding
Biological process: clathrin-dependent endocytosis; regulation of clathrin coat assembly; clathrin coat disassembly; synaptic vesicle recycling; synaptic vesicle uncoating
Cellular component: clathrin-coated vesicle; cytosol; postsynaptic density; vesicle; extrinsic component of presynaptic endocytic zone membrane; synapse
Genetic constraint (gnomAD): Loss-of-function variants: 33 observed, 106.13 expected, observed/expected ratio (o/e) 0.31, 90% interval 0.23 to 0.42. The upper end of that interval is the gene's LOEUF score, 0.42, which puts it in group 1 of 6, group 1 being the genes least tolerant of losing a copy. Missense variants: 1,001 observed, 1,213.6 expected, observed/expected ratio (o/e) 0.82, 90% interval 0.78 to 0.87. Synonymous variants: 396 observed, 438.26 expected, observed/expected ratio (o/e) 0.9, 90% interval 0.83 to 0.98.
Homologues: Orthologues: chimpanzee DNAJC6 (99% identical), macaque DNAJC6 (99% identical), pig DNAJC6 (96% identical), dog DNAJC6 (95% identical), rabbit DNAJC6 (93% identical), rat Dnajc6 (93% identical), mouse Dnajc6 (93% identical), guinea pig DNAJC6 (84% identical), tropical clawed frog dnajc6 (68% identical), zebrafish dnajc6 (60% identical). Paralogues in human: GAK (46% identical).
Diseases named in the same sentence as DNAJC6 in open-access papers:
DNAJC6 is named in the same sentence as 35 diseases in open-access papers, as found by Europe PMC text mining. Sharing a sentence is not in itself a finding about the gene and the disease. The quoted sentences say what the papers report.
Parkinson disease (34 papers, 2014 to 2026). A progressive degenerative disorder of the central nervous system characterized by loss of dopamine producing neurons in the substantia nigra and the presence of Lewy bodies in the substantia nigra and locus coeruleus. "Mutations in the DNAJC6 gene have been associated with mental retardation and Parkinson disease; early-onset obesity, mental retardation, and epilepsy were found in 7-year-old children with a homozygous 80 kb deletion in the chromosomal 1p31.3 region." (PMID 39771044, 2024). "Biallelic mutations in DNAJC6 cause a complex, early-onset neurodegenerative disorder characterized by rapidly progressive parkinsonism-dystonia in childhood." (PMID 38242634, 2024). "Our work is consistent with recent work on BioRxiv suggesting a role for pathogenic mutant DNAJC6/Auxilin at the Golgi26, and with synergistic genetic interactions between DNAJC6/Auxilin and Synj178, thus defining a new functional module in Parkinsonism." (PMID 36739293, 2023). "DNAJ heat shock protein family (Hsp40) member C6 (DNAJC6) is involved in the regulation of molecular chaperone activity through the stimulation of ATPase activity and is associated with Parkinson’s disease." (PMID 35625354, 2022). "Among them, DNAJC6 is a major risk factor for the early onset of Alzheimer’s and Parkinson’s diseases." (PMID 35456010, 2022). "Overall, our findings suggest that the mechanisms governing DNAJC6‐associated parkinsonism are likely to be multifactorial." (PMID 32472658, 2020). "Mutations in DNAJC6 are rare, but a likely under‐recognized cause of parkinsonism‐dystonia in infants and children." (PMID 32472658, 2020). "DNAJC6 encodes the neuronal protein Auxilin, and it is known have a role in clathrin-mediated endocytosis and to be implicated in the pathogenesis of Parkinson disease and intellectual disability." (PMID 30446675, 2018). "More recently additional quality control genes/mutations have been reported linked for Parkinsonism, including DNAJC6, DNAJC13, VPS35 and ATP6AP2." (PMID 25170892, 2014). "DNAJC6 is involved in synaptic vesicle recycling and efficient neurotransmission, with mutations associated with neurodevelopmental and synaptic defects and early-onset parkinsonism." (PMID 40223095, 2025). "Mutations in DNAJC6 gene are associated with mental retardation and early-onset Parkinson disease." (PMID 39771044, 2024). "To investigate the underlying disease mechanisms in childhood-onset DNAJC6 parkinsonism, we generated induced pluripotent stem cells (iPSC) from three patients harbouring pathogenic loss-of-function DNAJC6 mutations and subsequently developed a midbrain dopaminergic neuronal model of disease." (PMID 38242634, 2024). "Mutations in DNAJC6 were initially described in atypical Parkinsonism patients." (PMID 34093144, 2021). "Juvenile parkinsonism attributed to DNAJC6 mutations has only recently been reported." (PMID 32472658, 2020). "While HOOK1 interacts with CLN3, the causative gene for the autosomal recessive Batten disease characterized by visual impairment, gait anomalies, seizures, dementia and sometimes mental deterioration, DNAJC6 has been shown to be implicated in Parkinson disease." (PMID 26997977, 2016). "DNAJC6-related parkinsonism is typically characterized by disease onset in the second decade of life and rapid clinical progression until loss of walking within around 10 years from onset." (PMID 37047309, 2023). "Loci associated with rare monogenic forms of Parkinson’s disease, or more complex disorders with a prominent component of parkinsonism, also encode proteins involved in vesicle trafficking: VPS35, ATP13A2, PLA2G6, DNAJC6, SYNJ1, and VPS13C." (PMID 33556113, 2021). "Further atypical forms of parkinsonism, with juvenile onsets, include genes implicated in lysosomal function (ATP13A2) and synaptic vesicle endocytosis (SVE) pathway (DNAJC6 and SYNJ1)." (PMID 33381501, 2020).
Parkinson disease (continued). "Early onset LRRK2-related PD as well as milder forms of DNAJC6-related Parkinsonism may present with a phenotype resembling pure PRKN/PINK1 recessive cases." (PMID 34630269, 2021). "Additionally, we detected 4 P-SMRs involved in Alzheimer’s disease (Psen2), Parkinson’s disease (Dnajc6) and major depression disorder (Htr2a and Htr5a)." (PMID 32992647, 2020). "Moreover, atypical or complex parkinsonism may be due to mutations in genes such as ATP13A2, DCTN1, DNAJC6, FBXO7, PLA2G6, and SYNJ1." (PMID 35328025, 2022). "Finally, DNAJC6, SYNJ1 and SH3GL2 are associated with the disruption of synaptic vesicle endocytosis, which contributes to mitochondrial dysfunction and is thus related to the pathogenesis of Parkinson’s disease." (PMID 33686350, 2021). "Four well-characterized Parkinson disease genes, SNCA, LRRK2, DNAJC6, and PARKN, are situated within or adjacent to VERT regions." (PMID 40894531, 2025). "The mutants included in this study are ‘classical’ Parkinson disease genes, like LRRK2 and PINK1, and Parkinsonism genes that affect vesicle trafficking processes, including SYNJ1, DNAJC6/Aux. and RAB39B." (PMID 40178224, 2025). "Suspecting atypical Parkinsonism, a Wilson disease study and genetic tests of Charcot–Marie–Tooth (CMT), atypical Parkinsonisms (PARKs, GAB, DNAJC6, VPS13C, PINK, and LG), and atypical spinal–muscular atrophies (DYNC1H1, BICD, VAPB, GARS, DYNC1H1, mtATP6, and mtATP8) were carried out." (PMID 37510225, 2023). "Other genes such as APT13A2, PLA2G6, FBXO7, and the more recently identified DNAJC6, SYNJ1, and VPSC13 are usually related to younger onset Parkinsonism, complicated by atypical motor and non-motor phenotypes." (PMID 34630269, 2021).
Dystonia (3 papers, 2020 to 2024). An abnormally increased muscular tone that causes fixed abnormal postures. "DNAJC6 is an emerging cause of recessive juvenile parkinsonism‐dystonia." (PMID 32472658, 2020).
epilepsy (2 papers, 2020 to 2024). A brain disorder characterized by episodes of abnormally increased neuronal discharge resulting in transient episodes of sensory or motor neurological dysfunction, or psychic dysfunction. "Mutations in auxilin gene, DNAJC6, an important brain-specific protein in CCV uncoating, are associated with juvenile/early onset of PD and development of epilepsy and intellectual disability in addition to typical PD symptoms." (PMID 33240194, 2020).
hepatocellular carcinoma (2 papers, 2024). A malignant tumor that arises from hepatocytes. "A literature search revealed DNAJC6 possesses oncogenic properties and promotes hepatocellular carcinoma (HCC) progression through induction of epithelial–mesenchymal transition." (PMID 38475971, 2024). "LAPTI, composed of four lysosome‐related genes (CTSV, LAPTM4B, DNAJC6, AP1M2), is a reliable prognostic indicator for hepatocellular carcinoma patients and is validated in external data sets." (PMID 39695350, 2024).
hypertrophic cardiomyopathy (2 papers, 2023 to 2024). A condition in which the myocardium is hypertrophied without an obvious cause. "Concerning hypertrophic cardiomyopathy (HCM), specific circRNAs such as Circ TMEM56, Circ DNAJC6, and CircMBOAT2 have been identified with downregulated expression in individuals with HCM." (PMID 38474233, 2024). "In addition, serum circRNAs DNAJC6, TMEM56, and MBOAT2 were decreased in hypertrophic obstructive cardiomyopathy patients." (PMID 37323876, 2023).
Intellectual disability (2 papers, 2016 to 2024). "We propose six candidate genes (DAB1, HOOK1, DOCK7, DNAJC6, PDE4B, and NFIA) for the clinical features such as intellectual disability and OCD observed in DGDP005, because each of these genes is involved directly or indirectly in neurological disorders." (PMID 26997977, 2016). "We also determined the transcript levels of six candidate genes (DAB1, HOOK1, NFIA, DOCK7, DNAJC6 and PDE4B) for syndromic intellectual disability." (PMID 26997977, 2016). "Comparative deletion mapping showed that there are at least six candidate genes including, NFIA, HOOK1, DOCK7, DAB1, DNAJC6, and PDE4B, that could contribute to the syndromic or non-syndromic intellectual disability." (PMID 26997977, 2016).
Obesity (2 papers, 2022 to 2024). Accumulation of substantial excess body fat. "With DNAJC6-overexpressed 3T3-L1 cells (TgHsp), we investigated the new obesity mechanism caused by an energy imbalance." (PMID 35456010, 2022). "To date, there is a lack of studies on the mechanism of energy imbalance in obesity caused by overexpression or mutation of the DNAJC6 gene, an RMR-related gene." (PMID 35456010, 2022). "However, there has been no mechanistic study indicating that DNAJC6 deficiency or mutation leads to obesity thus far." (PMID 35456010, 2022). "Using significant RMR genes related to obesity founded by GWAS, such as MAP2K6 and DNAJC6, we identified various factors affecting RMR-based child obesity." (PMID 39771044, 2024). "Through our first report on the DNAJC6 gene related to RMR, we found a new mechanism related to energy metabolism in obesity." (PMID 35456010, 2022). "Our pilot GWAS reported that two genes, mitogen-activated protein kinase, kinase 6 (MAP2K6) and DnaJ Heat shock Protein Family Member C6 (DNAJC6), were distinguishingly related to both the resting metabolic rate (RMR) and body mass index (BMI) as biomarkers of obesity in children." (PMID 35456010, 2022). "In previous studies, the mechanism of obesity induction mediated by DNAJC6 was not established." (PMID 35456010, 2022).
Seizure (2 papers, 2020 to 2021). A seizure is an intermittent abnormality of nervous system physiology characterized by a transient occurrence of signs and/or symptoms due to abnormal excessive or synchronous neuronal activity in the brain. "Seizures also occur in some patients with mutations of DNAJC6 (PARK19), encoding auxilin, which has been implicated in the uncoating of synaptic vesicles, potentially resulting in alterations to synaptic vesicle recycling." (PMID 33841314, 2021).
Cerebellar atrophy (1 paper, 2020). Cerebellar atrophy is defined as a cerebellum with initially normal structures, in a posterior fossa with normal size, which displays enlarged fissures (interfolial spaces) in comparison to the foliae secondary to loss of tissue. "MRI brain imaging further corroborates this hypothesis; the mild generalized cerebral and/or cerebellar atrophy in 4 patients suggests that DNAJC6‐related disorders may also be associated with neuronal loss in other regions of the central nervous system." (PMID 32472658, 2020).
kidney cancer (1 paper, 2024). Primary or metastatic malignant neoplasm involving the kidney. "Several genes showed a low gDS in most kidney cancer cell lines, such as CD82, CD7, MEST, SELP, BMP6, CA2, DNAJC6, and VEPH1." (PMID 38728235, 2024).
lung carcinoma (1 paper, 2024). "DNAJC6 is the second most epimutated gene in all cancer samples and the most epimutated gene in the lung cancer cohort (43%)." (PMID 38475971, 2024). "DNAJC6 was the second most epimutated PTP gene in cancer patients and the most in lung cancer patients." (PMID 38475971, 2024).
malnutrition (1 paper, 2022). Inadequate nutrition resulting from poor diet, malabsorption, or abnormal nutrient distribution. "Since non-adipogenesis, non-glucose influx, non-ATP generation, and non-thermogenesis were found in the differentiation of DNAJC6-overexpressed cells, we need to know the next survival step in the case of continuous malnutrition, such as autophagy progress." (PMID 35456010, 2022).
prostate carcinoma (1 paper, 2022). A carcinoma that arises from epithelial cells of the prostate gland. "There were no previous descriptions for the fusions NAIP:OCLN, PDE1C:DNAJC6, KANSL1:ARL17B, FOXP2:CREM, and AHSA1:DLG3 in the context of prostate cancer." (PMID 35625354, 2022).
cancer (3 papers, 2020 to 2024). A tumor composed of atypical neoplastic, often pleomorphic cells that invade other tissues. "Overexpression of DNAJC6, as shown with increased promoter methylation in cancer subjects, was observed to enhance cell proliferation and invasion suggesting DNAJC6 hypermethylation may be assayed as a putative biomarker for poor outcome in HCC." (PMID 38475971, 2024). "Collectively, the roles of DNAJC6, IGF2BP3, and ZC3H13 in regulating cancer progression as mentioned in above studies are consistent with our present study, indicating the results based on our study are reliable." (PMID 34312475, 2021).
tumor (3 papers, 2017 to 2021). "Another study observed DNAJC6 was significantly upregulated in HCC and significantly correlated with tumor progression and poor outcome of HCC patients." (PMID 34312475, 2021). "The Basal subtype showed the highest number of specific upregulated genes (DNAJC2, DNAJC6, HSPA5, HSPA14 and CRYAA), DNAJA3 and CCT2 were upregulated in Luminal B, and DNAJB3 was only upregulated in HER2 tumours." (PMID 29954368, 2018).
movement disorder (2 papers, 2021 to 2024). Neurological conditions resulting in abnormal voluntary or involuntary movement, which may impact the speed, fluency, quality and ease of movement. "This Movement Disorder Society Genetic mutation database Systematic Review focuses on monogenic atypical parkinsonism with mutations in the ATP13A2, DCTN1, DNAJC6, FBXO7, SYNJ1, and VPS13C genes." (PMID 34396589, 2021).
brain diseases (1 paper, 2026). "Given the chaperone role of DNAJC6 in cellular homeostasis in adult neurons, we hypothesized that DNAJC6 dysfunction may not be limited to juvenile-onset disorders but could also be associated with adult-onset brain diseases." (PMID 41955024, 2026).
infection (1 paper, 2014). The state of being infected such as from the introduction of a foreign agent such as serum, vaccine, antigenic substance or organism. "In contrast, Dnaja4, Dnajb1a, Dnajc5aa, Dnajc6, and Dnajc16L were up-regulated in at least two time points after infection, suggesting their up-regulated expression was more lasting." (PMID 25542027, 2014).
DNAJC6 also shares sentences with these, for which no sentence is quoted: Parkinsonism (11 papers); Onset (4); cognitive decline (2); neurodegenerative disease (2); Alzheimer disease (1); cerebrotendinous xanthomatosis (1); Childhood onset (1); dementia (1); Dravet syndrome (1); frontotemporal dementia (1); hereditary ataxia (1); major depression disorder (1); neurofibromatosis type 1 (1); neurological disorders (1); Rett syndrome (1); Wilson disease (1); –muscular atrophies (1).